APC (APC regulator of Wnt signaling pathway)
Diseases named in the same sentence as APC in open-access papers (continued):
Sharing a sentence is not in itself a finding about the gene and the disease.
colon carcinoma (continued). "In addition, in a colon cancer mouse model with the APC mutation (ApcMin/+), neither miR-34a- nor miR-34b/c-deletion had a significant effect; however, the combined deletion of all three miR-34 members enhanced ApcMin/+-induced intestinal tumorigenesis." (PMID 30700696, 2019). "The apcmcr zebrafish is an established tool for understanding the genetics of colon cancer progression, and using the restoration of intestinal differentiation in homozygous apcmcr embryos as a readout has helped previously to uncover novel genes downstream of APC." (PMID 31231471, 2019). "Furthermore, these results suggest that the β-catenin levels could be modulated by LOX-1, interfering with the function of the tumor suppressor APC, which in colon cancer is usually present in a truncated form." (PMID 31608230, 2019). "Furthermore, they stand in contrast to what has been noted for other tumor suppressor genes, for example, in colon cancer models where reversible APC suppression promoted the expansion of undifferentiated cells that readily underwent differentiation upon APC restoration." (PMID 30014851, 2018). "Thus, targeting Prx II have potential therapeutic effects to treat colorectal cancers with and without APC mutations as it is already proved the increasing sensitivities of colon cancers to existing chemo and radiotherapy by inhibiting Prx II expression." (PMID 30177619, 2018). "Our study found that PKM2 is not required for colon tumor initiation or growth driven by APC loss." (PMID 29214019, 2017). "Taken together, these results argue that PKM2 is not required for APC-deficient colon cancer." (PMID 29214019, 2017). "For example, germline APC truncation causes an inherited autosomal condition called Familial Adenomatousis Polyposis (FAP), which almost exclusively results in an increased risk in developing colon cancer but with only a limited increase in the incidence of other malignancies." (PMID 27355964, 2016). "Butyrate alone does not induce apoptosis in colon cancer cells with the APC gene mutation, but combined treatment with DIM accentuates the ability of butyrate to induce apoptosis in these butyrate-resilient cells by downregulating Survivin, both in vitro and in vivo." (PMID 27447608, 2016). "Then we identified APC somatic mutation in this patient, and this imply that mutation of APC may contribute to tumorigenesis, but we cannot tell if it is an initiating event for FAP or colon cancer." (PMID 25617745, 2015). "In non-small cell lung carcinoma (NSCLC), unlike in colon cancer, mutations in β-catenin and APC genes are uncommon; thus, the mechanism underlying the constitutive activation of Wnt signalling in NSCLC remains unclear." (PMID 26468775, 2015). "In addition to APC, the β-catenin cellular level is also regulated through a direct proteasomal targeting mediated by RXRα and downregulation of RXRα in human and rodent colonic tumors has been reported previously." (PMID 26500891, 2015). "In addition, given the fact that USP22 is abnormally upregulated and there are gene alterations in several components of the APC/C complex in human colon cancers, it will be interesting to investigate whether these two events are positively associated." (PMID 27030811, 2015).
colon carcinoma (continued). "Indeed, miR-135 was found to be upregulated in colon tumors and correlated with low level of APC, which could exert an effect on colon cancer via regulating Wnt/β-catenin signaling pathway in colon cancer." (PMID 26064956, 2015). "In addition, RKO cells have intact Wnt components, unlike many colon cancer cells, which carry mutations in APC or β-catenin." (PMID 25236598, 2014). "We demonstrate that PI3K signaling is required for high WNT signaling activity in APC-mutated colon cancer cells, thus providing a means of how external stimuli, e.g. from the tumor microenvironment, may modulate WNT signaling in colon cancer cells through differential activation of PI3K." (PMID 24930890, 2014). "However, the metastatic suppressor function of shTMED3 in HT29 cells, albeit reduced in comparison with CC14, appears consistent with the recent finding that ligand signaling is still required for full WNT-TCF pathway activity and responses in APC-mutant colon cancer cells." (PMID 24920608, 2014). "Similarly, the interaction between Axin and the 20R2 of APC from colon cancer cells (truncated before the SAMP repeats) might be concealed by the presence of an already known Axin-binding site located before the 20R2." (PMID 24722208, 2014). "None of these variants occurred in genes associated with colon cancer, such as APC and β-catenin." (PMID 24498620, 2013). "In this study, we evaluated the cytotoxic activity of the extracts against three colon cancer cell lines with varying molecular characteristics, HT-29 (APC, type II truncation and COX-2 constitutive expression), HCT-15 (COX-2 deficient) and HCT 116 (APC, wild-type and COX-2 inducible)." (PMID 22898370, 2012). "Importantly, WLS siRNA does not affect BAR-luciferase activity in SW480 colon cancer cells, which harbour APC mutations leading to constitutive activation of β-catenin-dependent transcription in the absence of WNT stimulation." (PMID 23129487, 2012). "Since APC mutations are much rarer in breast cancer, it is likely that cell cycle genes (and specifically cell cycle control genes) do not harbor the same prognostic information as they do for colon cancer." (PMID 21176237, 2010). "However, unlike colon cancer, where either inactivating mutations in APC or activating mutations in β-catenin are observed in most cases, mutations in intracellular components of the Wnt signalling pathway in prostate cancer are rare." (PMID 19277043, 2009). "However, unlike colon cancer, mutations in APC and β-catenin are quite rare in gastric cancer, despite the occassional β-catenin accumulation in it." (PMID 19586554, 2009). "To further investigate the role of APC in repression, we tested the ability of Groucho to repress TOPFlash activity in colon cancer cell lines with wild type or variant APC proteins, predicting that Groucho would not be able to oppose β-catenin actions in cell lines with truncated APC proteins." (PMID 19460168, 2009). "Together, our results establish HMGA1 as an epigenetic gatekeeper of Wnt signals and cell state under conditions of APC inactivation, illuminating HMGA1 as a potential therapeutic target in colon cancer." (PMID 39895630, 2025). "Together, our results establish HMGA1 as an epigenetic gatekeeper of ASCL2 and Wnt signals, inflammation, and a stem-like state in colon cells with APC inactivation, highlighting HMGA1 as a promising potential therapeutic target in colon cancer." (PMID 39895630, 2025). "In a study conducted on a colon cancer cell line (HCT-116), Zn-stabilized adenomatous polyposis coli (APC) protein resulted in the inhibition of cell proliferation." (PMID 39330493, 2024). "Here, we described the phenotypic heterogeneity of APC-mutant tumors and identified RAI14 as a key prognostic determinant for APC-mutant colon cancer patients." (PMID 36934880, 2023).
colon carcinoma (continued). "Among all identified proteins, 5133 proteins quantified in more than 50% of both APC-MUT and APC-WT colon cancer cases with at least two identified unique peptides were used for subsequent data mining." (PMID 36934880, 2023). "We retrospectively analyzed spontaneous colon tumors from APC-KRAS and APC-KRAS-SLC25A22KO transgenic mice." (PMID 37542037, 2023). "We compared the overall gene expression profile of all 338 colon cancer cases obtained from the TCGA database, to reveal the relationship between APC-wt and APC-mt MSS/pMMR colon cancer." (PMID 35937946, 2022). "Further, we identified an imperfect but linear relationship between CHRM1 and APC and CTNNB1 mRNA levels, supporting a relationship between CHRM1/M1R and β-catenin signaling in colon cancer." (PMID 35370785, 2022). "NE promotes the progression of colon cancer via CREB1 activity‐dependent transcription, enhancing the expression of oncogenic miR‐373 and reducing the expression of the miR‐373 targets APC and TIMP2." (PMID 32118353, 2020). "We have demonstrated that NE promotes the progression of colon cancer via CREB1 activity‐dependent transcription, enhancing the expression of oncogenic miR‐373 and reducing the expression of the miR‐373 targets APC and TIMP2." (PMID 32118353, 2020). "We confirmed that proliferation and invasion of colon cancer cells are regulated in vitro and in vivo by miR‐373 through targeting of the tumor suppressors TIMP2 and APC." (PMID 32118353, 2020). "A study on APC and β-catenin phosphorylation and ubiquitination showed that, although colon cancer cell lines SW480 DLD-1 and HT-29 all have truncated APC, β-catenin ubiquitination and degradation were inhibited in SW480 but not in DLD-1 and HT29 cells." (PMID 32784494, 2020). "Our study reveals that NE promotes colon cancer cell proliferation and metastasis by activating the NE–CREB1–miR‐373 axis and demonstrates that the targets of miR‐373, TIMP2 and APC, mediate these NE‐induced effects." (PMID 32118353, 2020). "HuR inhibition in APC Min mice, a model of FAP and colon cancer, decreased the number of small intestinal tumors, and increased the abundance of Prevotella, Akkermansia, and Lachnospiraceae." (PMID 31620100, 2019). "After siRNA silencing of APC, β-catenin/CTNNB1 and Evi/Wls, changes in the transcriptome of HCT116 colon cancer cells were analyzed by RNA sequencing (RNAseq)." (PMID 29453334, 2018). "To investigate anti‐SIRPα mAb therapy‐induced inhibitory effects on sporadic colon cancer growth, we used a CDX2P9.5‐NLS Cre;APC+/FLOX (CPC‐APC) mouse model." (PMID 30460349, 2018). "In colon cancer, RIP140 interferes with the Wnt/β-catenin pathway through positive regulation of the tumor suppressor gene APC which in turn drives the degradation of β-catenin." (PMID 29340045, 2017).
colon carcinoma (continued). "Gene alterations in several components of the APC/C complex, including APC6/CDC16 and APC8/CDC23, have been found in human colon cancers." (PMID 27030811, 2015). "Notably, unlike β-catenin and APC mutations in colon cancer, these mutations are very rare in NSCLC20, 21; thus, understanding the biological basis for the observed deregulation of Wnt overactivation is of great value for future development of novel therapeutic strategies." (PMID 26468775, 2015). "Again, β-catenin whose stability is negatively regulated by APC, confers resistance to PI3K/Akt inhibitors in colon cancer." (PMID 25599599, 2015). "Also, mutant K-RAS may enhance β-catenin/TCF-dependent transcription in APC mutant K-RAS-dependent colon cancer cells by a mechanism involving bone morphogenetic protein (BMP)-7 secretion and autocrine signaling, leading to activation of TGF-β-activated kinase (TAK1)." (PMID 24202444, 2013). "The activation of Wnt signal, inhibition of APC/GSK3β/Axin complex, nuclear translocation of β-catenin, and up-regulation of Slug and Snail are key points of EMT regulation in colon cancer." (PMID 24039918, 2013). "For Number 1 with additional APC promoter, hypermethylation has a severe form of FAP with colon carcinomas and hepatoblastoma, the typical extracolonic manifestations." (PMID 22164339, 2011). "In DLD-1 and LS174T colon cancer cells, activation of the EP2 receptor by PGE2 promotes the release of glycogen synthase kinase 3β (GSK-3β) from the adenomatous polyposis coli (APC)/Axin/β-catenin complex." (PMID 22126303, 2011). "Triplicate wild-type TBE2 (-205C allele) increased reporter promoter activities four folds in SW620 cells (APC-/- colon cancer cells) and twelve folds in SW480 cells (APC-/- colon cancer cells) over the vector controls respectively." (PMID 22022540, 2011). "Furthermore, the finding of elevated levels of total APC mRNA is most likely a result of elevated levels of APC 1B mRNA expression, and does not argue directly against the theoretical, specific down-regulation of the APC 1A mRNA, the latter which is an observed phenomenon in colon cancer research." (PMID 20208994, 2010). "By studying the same orthologous genes in colon tumors from humans and the CRC mouse model B6 ApcMin/+, we found that bona fide cancer genes APC and SMAD4 were disrupted in both species." (PMID 20707908, 2010). "Surprisingly, there was no significant Groucho repression in APC type II, HT-29 or the APC wild type, β-catenin mutant, LS174T and HCT116 colon cancer cells (right)." (PMID 19460168, 2009). "The methylation status of the gene was compared with that observed in three usually hypermethilated genes (p16, APC, and MLH1) in 3 colon cancer cell lines (HCT116, CaCo2 and SW480) and in 30 paired tumour-normal tissues." (PMID 19257893, 2009). "The colon cancer cell line SW480, containing an APC protein truncated at amino acid 1338, produced similar results to those seen with Caco-2 cells (data not shown)." (PMID 16423286, 2006).
colon carcinoma (continued). "The noninvasive methodology might be useful for colon cancer models, e.g., CDX2, villin, and APC expression-based models, which often are used in long-term experiments, with few options for noninvasive monitoring of early tumor development." (PMID 37962942, 2024). "Colon cancer is a multistage disease characterized by successive changes in various genes, including Apc and Kras, leading to changes in CRC signaling pathways such as the APC Wnt/β-catenin and K-RAS." (PMID 37653904, 2023). "More importantly, we identified RAI14 as a key prognostic determinant for APC-mutant but not APC-wildtype colon cancer patients." (PMID 36934880, 2023). "In addition, we selected 42 patients' colon cancer tissues, including 22 cases of APC-mt/MSS and 20 APC-wt/MSS, to performed immunohistochemistry to further confirm that APC-wt/MSS contained more TIMT type I tumors, and had a higher DCR for ICIs." (PMID 35937946, 2022). "The ratio of risk of colon cancer, in those without and with an inherited driver mutation in the gene APC, rises linearly with age, supporting the PLM for colon cancer." (PMID 36000228, 2022). "The removal of the entire APC mRNA is not physiologically relevant to human colon cancer patients because most CRC patients retain APC N-terminal fragments." (PMID 34000297, 2021). "Sessile serrated tumors are a recently recognized class of colon cancers that present with BRAF mutations, as opposed to APC mutations, which are seen in the majority of colon cancer." (PMID 34138755, 2021). "Two colon cancer cell lines HCT-116 and DLD-1 used in our study have different genetic profile of APC and CTNNB1 genes that could lead to a different Wnt signaling response." (PMID 32784494, 2020). "Three hits at APC have also been shown to occur in tumors from attenuated FAP (AFAP) patients who have a milder phenotype with fewer colon polyps (average of 30) and a later age of colon cancer development." (PMID 32079164, 2020). "The weight of evidence indicates that relative expression of PPARβ/δ is not upregulated by APC/β-CATENIN/TCF4 signaling in colon cancer." (PMID 31602402, 2019). "To determine whether LEF1 expression is necessary to maintain the nuclear pool of β-catenin in colon cancer cells, we silenced LEF1 in DLD1 cells and in HCEC partially transformed by truncated APC." (PMID 31623618, 2019). "This relationship had a Pearson’s correlation coefficient of −0.5679 (P < 0.0001), indicating a strong negative correlation between miR-494 and APC expression levels in colon carcinomas." (PMID 29304823, 2018). "In our patient no pathogenic variants in the APC gene were found, but an identical activating CTNNB1 variant was present in both ovary and colon tumors." (PMID 29124495, 2018). "We also have shown that IWR-1 equally inhibits EMT of the colon carcinoma cell lines with (HT29, SW480, and SW620 cells) or without (HCT116 cells) APC mutation." (PMID 26450645, 2015).